FLT1 (fms related receptor tyrosine kinase 1)
Diseases named in the same sentence as FLT1 in open-access papers (continued):
Sharing a sentence is not in itself a finding about the gene and the disease.
chronic kidney disease (9 papers, 2014 to 2025). Impairment of the renal function secondary to chronic kidney damage persisting for three or more months. "This review article focuses on the function of PlGF/Flt-1 signaling and its regulation by soluble Flt-1 (sFlt-1) in chronic kidney disease (CKD)." (PMID 36430665, 2022). "Soluble Flt-1 (sFlt-1), an endogenous antagonist of the proatherogenic cytokine placental growth factor, is decreased in chronic kidney disease (CKD), leading to atherosclerotic progression." (PMID 31666542, 2019). "It was reported that a relationship exists between soluble Flt-1, coded by that gene, and mortality in chronic kidney disease patients, but the data have been insufficient to explain its biological effect." (PMID 27736948, 2016).
diabetic retinopathy (9 papers, 2011 to 2024). "have pinpointed six significant genes (CD44, CDC42, TIMP1, BMP7, RHOC, FLT1) as crucial for diabetic retinopathy through advanced bioinformatics analysis coupled with in vivo validation." (PMID 38605967, 2024).
neuroblastoma (9 papers, 2009 to 2026). Neuroblastoma (NB) is the most common solid, extracranial childhood tumor. "In the case of neuroblastoma, FLT1 expression was linked to chemoresistance, especially in the context of low oxygen tension." (PMID 20422012, 2010). "VEGF signaling plays a regulatory role in neuroblastoma angiogenesis via a paracrine mechanism through two specific tyrosine kinase VEGF receptors: VEGFR-1 (or Flt-1) and VEGFR-2 (or KDR) at the surface of the endothelial cells." (PMID 21876694, 2012). "Hypoxia upregulates VEGF expression and in conjugation with Flt-1 plays a pivotal role in VEGF-mediated autocrine signaling of tumor growth and angiogenesis in neuroblastoma cell line." (PMID 21876694, 2012). "We analyzed the expression of endothelial markers (EGFL7, FLT1, PTPRB33), mesenchymal cells (COL1A2, COL1A1, PDGFRB34,35) and immune markers (ITGAM, CD247, PTPRC36–38) in MYCN-amplified neuroblastoma patient samples (with at least 90% tumor purity) and tumors from Protocol #4." (PMID 39367051, 2024). "An autocrine loop has been described in neuroblastoma involving VEGF, Flt1 and ERK1/2 and our current data suggest that GLA may interfere with this loop leading to inhibition of tumour cell proliferation and survival in C6 cells in vivo." (PMID 19292920, 2009).
pulmonary fibrosis (9 papers, 2009 to 2024). Chronic progressive interstitial lung disorder characterized by the replacement of the lung tissue by connective tissue, leading to progressive dyspnea, respiratory failure, or right heart failure. "Endothelial-specific knockout of Flt1 reproduces the anti-fibrotic effect of microRNA-200c against pulmonary fibrosis and results in the secretion of a pool of soluble factors and matrix components able to promote epithelial transdifferentiation in a paracrine manner." (PMID 37454154, 2023). "Subsequent investigations have identified vascular endothelial growth factor receptor 1 (Flt1) as the primary functional target of miR-200c in endothelial cells, and Flt1 depletion can effectively replicate the anti-fibrotic effects of miR-200c on pulmonary fibrosis." (PMID 39479511, 2024). "Anti-VEGF gene therapy, soluble flt-1 (sflt-1), specific receptors for VEGFR1, also attenuates BLM-induced pulmonary fibrosis." (PMID 34082837, 2021). "While expression of genes coding for soluble mediators (e.g. cytokines) were unchanged, receptors for several mediators known to participate in lung fibrosis were up-regulated (CCR2, FGFR2, FLT1, IGF1R, IL1R1 and IL6R)." (PMID 23844029, 2013). "have shown that fms related receptor tyrosine kinase 1 (Flt1), produced by lung ECs, impedes the transdifferentiation of AT2 cells into AT1 cells, having a negative effect on lung repair in pulmonary fibrosis." (PMID 38405059, 2024).
astrocytomas (8 papers, 2015 to 2025). "Except for CCND2, FLT1, FOXC2, KDR, KRT14, and TEK, the mRNA expression ratio of cancer pathway-associated genes in the astrocytoma grade III cell line (SW1088) was comparable to that of other tumour cell lines." (PMID 36142793, 2022).
metastatic disease (8 papers, 2013 to 2025). "Using immunohistochemical staining of 170 ccRCC patients, VEGFR1 (FLT1) expression was associated with treatment response, histological grade and RECIST (Response Evaluation Criteria in Solid Tumors) score, whereas SAV1 and BLIMP1 (PRDM1) were associated with metachronous metastatic disease." (PMID 38999991, 2024).
acute myeloid leukemia (7 papers, 2007 to 2025). Acute myeloid leukemia (AML) is a group of neoplasms arising from precursor cells committed to the myeloid cell-line differentiation. "For instance, in acute myeloid leukemia (AML), the Kv11.1 (hERG1) associates with β1 integrin and the vascular endothelial growth factor (VEGF) receptor 1 (also known as Flt-1), to form a complex that modulates the cell proliferation and trans-endothelial migration signaling pathways." (PMID 37426811, 2023). "It is worth to mention that a few genes with a role in acute myeloid leukemia: GRB2, CSFIR, MARCKS and PDGFB were upregulated; FLT1, IL6, PIK3C2B, BALAP3 and MAPK10 were downregulated." (PMID 36413544, 2022). "In the acute myeloid leukemia, the macromolecular signaling complex formed by the hERG channel with VEGFR-1 (FLT-1) and β1 integrin was found to mediate the FLT-1-dependent cell migration and invasion." (PMID 24386436, 2013).
cervical cancer (7 papers, 2017 to 2024). A primary or metastatic malignant neoplasm involving the cervix. "Our results suggested that the relationships between TNFAIP8L1 and FLT1 polymorphisms and the risk of cervical cancer amongst Uyghur females." (PMID 31289124, 2019). "Three TNFAIP8L1 variants and one variant of FLT1 were associated with reduced cervical cancer susceptibility amongst females from Xinjiang Uyghur Autonomous Region of China." (PMID 31289124, 2019). "In the present study, selected SNPs in TNFAIP8L1 and FLT1 and their association with cervical cancer risk were investigated for the first time." (PMID 31289124, 2019). "The stratified analysis showed that TNFAIP8L1-rs10426502, -rs1060555, and FLT1-rs9513111 were associated with a decreased risk of cervical cancer amongst people older than 43 years." (PMID 31289124, 2019). "In this case-control study, we investigated the association between SNPs of TNFAIP8L1 and FLT1 genes and cervical cancer risk amongst Xinjiang Uygur females." (PMID 31289124, 2019). "Our study validated the relationship between TNFAIP8L1 and FLT1 variations and the risk of cervical cancer in Uygur women." (PMID 31289124, 2019). "In addition, rs10426502 and rs1060555 of TNFAIP8L1 were significantly associated with reduced risk of cervical cancer in the dominant and additive models, as well as rs9513111 of FLT1 was significantly associated with reduced risk of cervical cancer in the recessive model (P<0.05)." (PMID 31289124, 2019). "A PPIN of 90 genes identified FLT1, IGF2, IRS1, JUN, KDR, ZEB1, TIMP2 (downregulated), and EZH2, SOX2, and MYB (upregulated) in cervical cancer samples when compared with normal samples." (PMID 36879084, 2023). "TNFAIP8L1 and FLT1 play critical roles in the occurrence and development of tumors, but no in-depth studies have been carried out in cervical cancer." (PMID 31289124, 2019). "At present, the function of FLT1 in cervical cancer has not been deeply studied." (PMID 31289124, 2019).
esophageal cancer (7 papers, 2015 to 2024). A primary or metastatic malignant neoplasm involving the esophagus. "Previous studies have demonstrated that FLT1 expression is significantly correlated with OS in several cancers, including CRC, cholangiocarcinoma, and esophageal cancer." (PMID 35087751, 2021).
HELLP syndrome (7 papers, 2015 to 2025). A life-threatening condition that can potentially complicate pregnancy. "We conclude that a double-dose A allele in one FLT1 polymorphism (rs7993594), expressed maternally, appears to be associated with increased risk of HDP and a double dose of the G-t-G-G haplotype (rs7993594, rs3751395, rs7983774, rs664393) is associated with severe-spectrum PE/HELLP syndrome." (PMID 39806130, 2025).
renal carcinoma (7 papers, 2015 to 2024). A carcinoma arising from the epithelium of the renal parenchyma or the renal pelvis. "Among those, the colon, stomach and renal cancer cell lines had more frequent FLT1 hypermethylation than the other cancer cell lines." (PMID 32041578, 2020). "Next, we tested for associations between expression and methylation of FLT1 and KDR in renal cancer tissues." (PMID 26380584, 2015). "In the present study, we aimed to analyze whether epigenetic alterations in FLT1 and/or KDR are related to the anti-cancer effects of drugs targeting VEGF-VEGFR signaling in renal cancer cells (RCCs) and in tissues collected from renal cancer patients." (PMID 26380584, 2015). "To evaluate whether epigenetic gene silencing occurs in renal cancer tissue, we analyzed the relationship between promoter methylation and expression of VEGF, FLT1, and KDR in normal vs. cancer tissues collected from eight renal cancer patients." (PMID 26380584, 2015). "In contrast, renal cancer tissues from nonresponders to sunitinib had average of 20 % methylation at the FLT1 promoter." (PMID 26380584, 2015). "Here, we evaluated the effects of FLT1 and KDR promoter hypermethylation combined with drugs targeting VEGF-VEGFR signaling on cancer-related phenotypes in renal cancer cells (RCCs) and examined changes in FLT1 and KDR promoter hypermethylation in tissues from patients with renal cancer." (PMID 26380584, 2015). "To evaluate whether the methylation statuses of VEGF, FLT1, or KDR of renal cancer tissues are related to patient responses to sunitinib, we compared the methylation statuses of these targets in cancer tissues from 13 patients with RCC who were treated with sunitinib." (PMID 26380584, 2015).
brain tumors (6 papers, 2007 to 2024). "Similarly, ETS1 had also been studied for its impact in the expression/regulation of other genes in brain tumors, such as uPA and Flt-1/VEGFR-1 in astrocytic tumors and DPP-III when conjugated with Elk-1 in human GBM." (PMID 33801334, 2021). "VEGF in brain tumors is both tumor- and EC-derived and therefore exerts its effects in a paracrine and autocrine fashion through high affinity binding to the tyrosine kinase receptors VEGFR2/Flk-1 and VEGFR1/Flt-1." (PMID 33036204, 2020).
cholangiocarcinoma (6 papers, 2013 to 2023). A carcinoma that arises from the intrahepatic biliary tree (intrahepatic cholangiocarcinoma) or from the junction, or adjacent to the junction, of the right and left hepatic ducts (hilar cholangiocarcinoma). "There is however only limited data available for the expression of FLT1/VEGFR1 in cholangiocarcinoma though Rogler and others suggested a potential association with a more aggressive phenotype." (PMID 23704979, 2013). "EGFR and FLT1 seem to be potential markers to identify those patients at high risk of dying from cholangiocarcinoma." (PMID 23704979, 2013). "The significant associations of EGFR, FLT1 and HPSE gene expression with survival warrant prospective evaluation of their usability in selecting more efficient treatment strategies for patients with cholangiocarcinoma." (PMID 23704979, 2013). "We determined the gene expressions of FLT1, FLT4, HPSE, Hif1a, HB-EGF, PDGFA, PDGF-RA and EGFR in FFPE samples of patients with cholangiocarcinoma." (PMID 23704979, 2013). "All three factors (expression of FLT1, HPSE and EGFR) were tested with ROC Analysis for their potential predictive capabilities in identifying patients with cholangiocarcinoma with a prolonged overall survival time (>3 years)." (PMID 23704979, 2013).
heart failure (6 papers, 2018 to 2024). Inability of the heart to pump blood at an adequate rate to meet tissue metabolic requirements. "All these functional data implied that eNOS overexpression from the combination of the EC71 vector and Flt-1 promoter contributed to the partial recovery of cardiac systolic and diastolic functions in mice with heart failure." (PMID 34485601, 2021). "A subsequent larger study by the same group revealed that plasma soluble Flt-1 level was again negatively correlated with estimated GFR and associated with severity of heart failure and mortality in 586 patients with coronary artery disease." (PMID 29937525, 2018). "Another study of 1403 US patients with heart failure also showed that estimated GFR decreased with increasing quartile of plasma soluble Flt-1." (PMID 29937525, 2018). "Examples of angiogenesis-related genes that are specifically induced in human heart failure but not in mouse models include receptors such as the VEGF-receptor FLT1 or transcription factors like the mesenchyme homeobox protein 2 (MEOX2)." (PMID 38573186, 2024).
invasive breast carcinoma (6 papers, 1999 to 2019). A carcinoma that infiltrates the breast parenchyma. "In invasive breast cancer, expression of Flt-1 and KDR has been observed in 44 and 38% of cases, respectively." (PMID 15841074, 2005). "A three-step immunohistochemical method was applied to paraffin-embedded sections from 154 patients with invasive breast carcinoma in order to detect expressions of the proteins EGFR, pEGFR, oestrogen receptor, progesterone receptor, c-erbB-2, pAkt, VEGFR-1/Flt-1, MMP-14 and uPAR." (PMID 18522728, 2008).
malaria (6 papers, 2010 to 2023). Malaria is a serious and sometimes fatal disease caused by a parasite that commonly infects a certain type of mosquito which feeds on humans. "The short alleles of the FLT1 repetitive region are deleterious during malaria season but appear to be beneficial out of malaria season." (PMID 20976248, 2010). "In addition, there was reduced expression of the pro-angiogenic factor Vegf-a (P < 0.01) and its negative regulator Flt-1 (P < 0.05) in placental tissue from malaria-infected dams receiving L-arginine supplementation compared to malaria-infected control dams." (PMID 29514999, 2018). "Within the severe malaria group there was a significant difference in flt-1 in neurons with a lower frequency found in the diencephalon compared with the brainstem (P = 0.001) but not between cortex and brainstem (P = 0.22) or cortex and diencephalon (P = 0.13)." (PMID 20716170, 2010). "We identified novel host biomarkers of pediatric severe and fatal malaria (soluble TREM-1 and soluble Flt-1) and generated simple biomarker combinations that accurately predicted death in an African pediatric population." (PMID 21364762, 2011). "VEGF, VEGFR1 (flt-1), VEGFR2 (flk-1) and phosphorylated VEGFR2 (pKDR) were expressed in both control and severe malaria cases." (PMID 20716170, 2010).
medulloblastoma (6 papers, 2010 to 2025). A malignant, invasive embryonal neoplasm arising from the cerebellum. "Our study found up-regulation of Vegfa, Flt1, and Hbegf in SmoA1 +; Pten +/− medulloblastomas." (PMID 20520772, 2010).
placental insufficiency (6 papers, 2017 to 2025). Failure of the placenta to deliver an adequate supply of nutrients and oxygen to the fetus. "The suggested pathogenic mechanisms of ENG, LEP, and FLT1 related to placental insufficiency IUGR needs further validation in cell and/or animal model." (PMID 35090410, 2022). "ENG, LEP, and FLT1 were identified as key genes related to placental insufficiency IUGR, Significantly higher expression of ENG and LEP at RNA level in this disease was validated reliable by three GEO datasets repeatedly." (PMID 35090410, 2022). "The expression of genes ENG, LEP, and FLT1 were significantly upregulated in placental insufficiency IUGR." (PMID 35090410, 2022).
sarcoma (6 papers, 2013 to 2020). A usually aggressive malignant neoplasm of the soft tissue or bone. "The expression levels of sunitinib targeted-kinases were measured by transcriptome sequencing for PDGFRA/B, KIT, RET, FLT1(VEGFR1), KDR (VEGFR2), and FLT4(VEGFR3) for patient cohort with EMC and other sarcoma histologies." (PMID 28423517, 2017).
clear cell renal cell carcinoma (5 papers, 2015 to 2022). "In clear-cell renal cancer, eight differentially expressed genes were identified as biomarkers, including VEGFA, FLT1, FN1, and others." (PMID 32070055, 2020).
emphysema (5 papers, 2009 to 2022). "In the emphysematous tissues of WT mice treated with 4 week PPE, VEGF R1 (Flt-1) expression decreased as compared to the WT control mice with saline that had no emphysema." (PMID 19930612, 2009).
Infertility (5 papers, 2017 to 2025). "We evaluated the association of five polymorphic variants in VEFGA (rs699947), FLT1 (rs722503), KDR (rs2071559, rs1870377) and FGF2 (rs308395) genes with infertility and recurrent implantation failure among Polish women." (PMID 36901702, 2023).
lymphoma (5 papers, 2014 to 2022). A malignant (clonal) proliferation of B- lymphocytes or T- lymphocytes which involves the lymph nodes, bone marrow and/or extranodal sites. "Mean uptake of FLT-1 in lymphoma manifestations (mean FLT-1 SUV) was 7.3 (range 1.0 – 18.2)." (PMID 24979177, 2014).
Miscarriage (5 papers, 2014 to 2025). A pregnancy that ends at a stage in which the fetus is incapable of surviving on its own, defined as the spontaneous loss of a fetus before the 22th week of pregnancy. "Indeed, decreased maternal blood concentrations of sFlt-1 in the first trimester are associated with miscarriages, supporting the idea that the protective mechanisms of Flt-1/sFlt-1 may also similarly function in early human pregnancy." (PMID 25393290, 2014). "Quantitative in vitro and in vivo experiments, involving the treatment of cultured endothelial progenitor cells with soluble Flt1, demonstrated a reduction in the frequency of miscarriage through the VEGF-PI3K/Akt-endothelial nitric oxide synthase pathway in a mouse recurrent miscarriage model." (PMID 40076883, 2025).
peripartum cardiomyopathy (5 papers, 2018 to 2024). Peripartum cardiomyopathy (PPCM) is an idiopathic, potentially fatal form of dilated cardiomyopathy that develops during the final month of pregnancy or within five months after delivery. "Elevated levels of the VEGF inhibitor soluble Flt1 (VEGFR1) were observed in plasma samples of women with peripartum cardiomyopathy, and exogenous administration of soluble Flt1 into mice produced diastolic dysfunction." (PMID 30895179, 2019).
pregnancy disorder (5 papers, 2021 to 2023). A disorder that is related to pregnancy. "Among the double-SNP variants, the TT complex genotypes for CSF2 rs25881 and FLT1 rs722503 polymorphisms correlated with an increased risk of PROM and pPROM, after adjusting for APTT, PLT parameters or pregnancy disorders." (PMID 34828331, 2021). "We found in our study that genetic changes, localized in SNPs from CSF2, FLT1, TFPI and TLR9 genes, were associated with PROM, when the results had been adjusted for APTT, PLT parameters or pregnancy disorders." (PMID 34828331, 2021). "A multiple-SNP analysis showed that the TT variants for CSF2 and FLT1 polymorphisms correlated with an approximately two-fold increase in the PROM risk when corrected for APTT, PLT parameters and pregnancy disorders (p ≤ 0.050)." (PMID 34828331, 2021). "Similarly, the TT double-SNP variants for the CSF2 and FLT1 polymorphisms had an approximately two-fold increased risk of PROM when the results were adjusted for DM and other pregnancy disorders." (PMID 34828331, 2021). "An additional comparison between the pPROM and tPROM cases showed that the C alleles for the CSF2, FLT1 and TFPI polymorphisms, and the T allele for the TLR9 SNP in different complex variants, were more common in the women with pPROM after adjusting for APTT, PLT parameters and pregnancy disorders." (PMID 34828331, 2021).